SYK (spleen associated tyrosine kinase)
Description:
Non-receptor tyrosine kinase which mediates signal transduction downstream of a variety of transmembrane receptors including classical immunoreceptors like the B-cell receptor (BCR). Regulates several biological processes including innate and adaptive immunity, cell adhesion, osteoclast maturation, platelet activation and vascular development. Assembles into signaling complexes with activated receptors at the plasma membrane via interaction between its SH2 domains and the receptor tyrosine-phosphorylated ITAM domains. The association with the receptor can also be indirect and mediated by adapter proteins containing ITAM or partial hemITAM domains. The phosphorylation of the ITAM domains is generally mediated by SRC subfamily kinases upon engagement of the receptor. More rarely signal transduction via SYK could be ITAM-independent. Direct downstream effectors phosphorylated by SYK include DEPTOR, VAV1, PLCG1, PI-3-kinase, LCP2 and BLNK. Initially identified as essential in B-cell receptor (BCR) signaling, it is necessary for the maturation of B-cells most probably at the pro-B to pre-B transition. Activated upon BCR engagement, it phosphorylates and activates BLNK an adapter linking the activated BCR to downstream signaling adapters and effectors. It also phosphorylates and activates PLCG1 and the PKC signaling pathway. It also phosphorylates BTK and regulates its activity in B-cell antigen receptor (BCR)-coupled signaling. In addition to its function downstream of BCR also plays a role in T-cell receptor signaling. Also plays a crucial role in the innate immune response to fungal, bacterial and viral pathogens. It is for instance activated by the membrane lectin CLEC7A. Upon stimulation by fungal proteins, CLEC7A together with SYK activates immune cells inducing the production of ROS. Also activates the inflammasome and NF-kappa-B-mediated transcription of chemokines and cytokines in presence of pathogens. Regulates neutrophil degranulation and phagocytosis through activation of the MAPK signaling cascade (By similarity). Required for the stimulation of neutrophil phagocytosis by IL15. Also mediates the activation of dendritic cells by cell necrosis stimuli. Also involved in mast cells activation. Involved in interleukin-3/IL3-mediated signaling pathway in basophils (By similarity). Also functions downstream of receptors mediating cell adhesion. Relays for instance, integrin-mediated neutrophils and macrophages activation and P-selectin receptor/SELPG-mediated recruitment of leukocytes to inflammatory loci. Also plays a role in non-immune processes. It is for instance involved in vascular development where it may regulate blood and lymphatic vascular separation. It is also required for osteoclast development and function. Functions in the activation of platelets by collagen, mediating PLCG2 phosphorylation and activation. May be coupled to the collagen receptor by the ITAM domain-containing FCER1G. Also activated by the membrane lectin CLEC1B that is required for activation of platelets by PDPN/podoplanin. Involved in platelet adhesion being activated by ITGB3 engaged by fibrinogen. Together with CEACAM20, enhances production of the cytokine CXCL8/IL-8 via the NFKB pathway and may thus have a role in the intestinal immune response (By similarity).
Synonyms: IMD82; p72-Syk
Tractability: Small molecule: an approved drug acts on it; a structure with a bound ligand is known; a high-quality ligand is known; it has a high-quality binding pocket; it belongs to a druggable protein family. Antibody: UniProt places it where antibodies can reach, with high confidence; its Gene Ontology location is reachable by antibodies, with high confidence; the Human Protein Atlas places it where antibodies can reach. PROTAC: UniProt records ubiquitination sites on it; ubiquitination databases record sites on it; its protein half-life has been measured; a small molecule that binds it is known.
Target class: Tyrosine protein kinase Syk family; TK protein kinase group; Enzyme; Protein Kinase; Kinase
Chemical probes: BI 1002494 (high quality), ENTOSPLETINIB (high quality), MRL-SYKi (high quality), PD083017, PD083306, PD084627, PD085040, PD085309, PRT062607 (high quality), Syk inhibitor II
Gene: Protein-coding gene on chromosome 9 (90,801,579 to 90,898,549, forward strand). Ensembl gene ENSG00000165025.
Subcellular location: Cell membrane; Cytoplasm, cytosol
Subcellular location (Human Protein Atlas): Cytosol; Plasma membrane; Vesicles
Pathways (Reactome):
Immune System: Antigen activates B Cell Receptor (BCR) leading to generation of second messengers; CLEC7A (Dectin-1) signaling; DAP12 signaling; Dectin-2 family; FCERI mediated Ca+2 mobilization; FCERI mediated MAPK activation; FCGR activation; FLT3 signaling through SRC family kinases; Fc epsilon receptor (FCERI) signaling; Inactivation of CSF3 (G-CSF) signaling; Interleukin-2 signaling; Regulation of actin dynamics for phagocytic cup formation; Regulation of signaling by CBL; Role of LAT2/NTAL/LAB on calcium mobilization; Role of phospholipids in phagocytosis; Signaling by CSF3 (G-CSF)
Disease: FCGR3A-mediated IL10 synthesis; FCGR3A-mediated phagocytosis; Potential therapeutics for SARS
Hemostasis: GPVI-mediated activation cascade
Signal Transduction: Integrin signaling
Gene Ontology:
Molecular function: integrin binding; interleukin-15 receptor binding; kinase activity; non-membrane spanning protein tyrosine kinase activity; phospholipase binding; phosphotyrosine residue binding; protein binding; protein kinase activity; protein serine/threonine kinase activity; protein tyrosine kinase activity; scaffold protein binding; signaling receptor binding; ATP binding; phosphatase binding; protein kinase binding; SH2 domain binding; Toll-like receptor binding
Biological process: amyloid-beta clearance; antiviral innate immune response; apoptotic signaling pathway; B cell receptor signaling pathway; cell surface pattern recognition receptor signaling pathway; cellular response to amyloid-beta; cellular response to lipid; intracellular signal transduction; leukocyte cell-cell adhesion; neutrophil chemotaxis; positive regulation of B cell differentiation; positive regulation of cGAS/STING signaling pathway; positive regulation of inflammatory response; positive regulation of interleukin-10 production; positive regulation of interleukin-12 production; positive regulation of interleukin-6 production; positive regulation of interleukin-8 production; positive regulation of monocyte chemotactic protein-1 production; positive regulation of protein-containing complex assembly; positive regulation of superoxide anion generation; positive regulation of toll-like receptor 9 signaling pathway; positive regulation of TORC1 signaling; positive regulation of tumor necrosis factor production; protein import into nucleus; protein phosphorylation; and 41 more
Cellular component: cytoplasm; nucleus; protein-containing complex; T cell receptor complex; cytosol; early phagosome; plasma membrane; B cell receptor complex
Genetic constraint (gnomAD): Loss-of-function variants: 16 observed, 80.48 expected, observed/expected ratio (o/e) 0.2, 90% interval 0.13 to 0.3. The upper end of that interval is the gene's LOEUF score, 0.3, which puts it in group 1 of 6, group 1 being the genes least tolerant of losing a copy. Missense variants: 529 observed, 843.49 expected, observed/expected ratio (o/e) 0.63, 90% interval 0.58 to 0.67. Synonymous variants: 312 observed, 319.82 expected, observed/expected ratio (o/e) 0.98, 90% interval 0.89 to 1.07.
Homologues: Orthologues: chimpanzee SYK (99% identical), macaque SYK (99% identical), pig SYK (93% identical), rabbit SYK (92% identical), dog SYK (92% identical), mouse Syk (91% identical), rat Syk (91% identical), guinea pig SYK (83% identical), tropical clawed frog syk (70% identical), zebrafish syk (68% identical). Paralogues in human: ZAP70 (54% identical), LCK (28% identical), ABL2 (27% identical), SRC (27% identical), ABL1 (27% identical), FYN (27% identical), YES1 (27% identical), FRK (26% identical), HCK (26% identical), CSK (26% identical), BLK (26% identical), LYN (26% identical), and 20 more.
Diseases named in the same sentence as SYK in open-access papers:
SYK is named in the same sentence as 264 diseases in open-access papers, as found by Europe PMC text mining. Sharing a sentence is not in itself a finding about the gene and the disease. The quoted sentences say what the papers report.
lymphoma (45 papers, 2012 to 2025). A malignant (clonal) proliferation of B- lymphocytes or T- lymphocytes which involves the lymph nodes, bone marrow and/or extranodal sites. "Targeting SYK in combination with ibrutinib produces synthetic lethality, providing a framework for the clinical investigation of ibrutinib with SYK inhibitors in MYD88-mutated lymphomas." (PMID 32005797, 2020). "We next performed PhosFlow studies for SYK in MYD88-mutated lymphoma cells following treatment with a MYD88 inhibitor or control peptide." (PMID 32005797, 2020). "The findings provide a framework for the clinical investigation of ibrutinib with SYK inhibitors in MYD88-mutated lymphomas." (PMID 32005797, 2020). "Cell viability analysis showed that combining ibrutinib and SYK inhibitors triggered synthetic killing of MYD88-mutated lymphoma cells." (PMID 32005797, 2020). "We therefore investigated a role for SYK as a mediator of TLR/BCR cross talk in MYD88-mutated lymphomas." (PMID 32005797, 2020). "Our findings extend the spectrum of mutated MYD88 pro-survival signaling to include SYK directed BCR cross talk in MYD88-mutated lymphomas." (PMID 32005797, 2020). "We therefore investigated a role for SYK as a mediator of BCR activation in MYD88-mutated lymphomas." (PMID 32005797, 2020). "Deregulated SYK has been implicated in various malignancies, including lymphoma, leukemia, and breast cancer (25, 56, –, 58)." (PMID 30135222, 2018). "Constitutive activation of SYK by gene fusion or overexpression has been implicated in hematopoietic malignancies, and SYK inhibitors have shown promise in clinical trials for lymphoma and leukemia." (PMID 25699542, 2015). "Furthermore, the increased SYK activation resulted in the clinical manifestation of immune dysregulation, organ inflammation, and a predisposition for lymphoma." (PMID 42004161, 2024). "Furthermore, by knockdown studies as well as use of SYK inhibitors, we validated the importance of SYK as an essential pro-survival molecule in MYD88-mutated lymphoma cells." (PMID 32005797, 2020). "Importantly, the combination of SYK inhibitors with ibrutinib yielded synergistic lethality in MYD88-mutated lymphoma cells." (PMID 32005797, 2020). "This hallmark of B cell–derived lymphoma is considered an oncogenic and prosurvival signal and underlies the rationale for using BCR inhibitors to target downstream kinases such as BTK, SYK, and PI3Kδ." (PMID 38048228, 2024). "For example, compared with normal tissues, the brain tumors and breast tumors hold much higher expression of SYK, while the level of SYK is lower in leukemia and lymphoma." (PMID 36568669, 2022). "The alignment of the networks reconstructed from the different datasets allowed us to demonstrate that protein interactions of some SYK targets common to the networks were profoundly modified between the breast cancer and lymphoma networks." (PMID 33670716, 2021). "The SYK gene possesses dual characteristics of a tumor promoter gene within various lymphomas, leukemias, carcinomas, and cancer types (lung cancer, ovarian cancer, and small cell lung cancer)." (PMID 34575665, 2021). "Through the signaling of the B-cell receptor, SYK acts as a key modulator in various B cell-driven lymphomas." (PMID 34575665, 2021). "We identified activated SYK (p-SYK), a component of BCR in complex with MYD88 in MYD88-mutated WM and ABC DLBCL lymphoma cells." (PMID 32005797, 2020). "Since SYK was activated by mutated MYD88, we next sought to clarify if SYK and p-SYK were present in the “Myddosome” signaling complex in MYD88-mutated lymphoma cells." (PMID 32005797, 2020). "Further to these findings, we performed cellular co-localization experiments using immunofluorescent (IF) with antibodies for MYD88 and SYK in both MYD88-mutated and wild-type lymphoma cells." (PMID 32005797, 2020). "Few investigational SYK inhibitors have shown limited efficacy in various hematologic malignancies, including lymphoma and leukemia." (PMID 30135222, 2018).
lymphoma (continued). "In our current study, we showed an increase in SYK phosphorylation in LMP2A-positive MYC-induced lymphoma and that targeting SYK with a novel SYK inhibitor, TAK-659, completely inhibited splenomegaly and tumorigenesis." (PMID 30135222, 2018). "Piceatannol, a SYK selective inhibitor, exhibited anticancer abilities by inhibiting proliferation and inducing apoptosis in many different tumors, including leukemia, lymphoma, melanoma, prostate and colon cancers." (PMID 29137391, 2017). "SYK reported as an oncogene in B cell leukemia and lymphomas, head and neck cancer, ovarian cancer and retinoblastoma, has made this kinase a popular target for the development of therapeutic agents." (PMID 26934445, 2016). "Herein, we investigated the anti-lymphoma activity of cerdulatinib, a novel compound that dually targets SYK and JAK/STAT pathways." (PMID 26575169, 2015). "The identification of SYK as a molecular target in B-lineage leukemia/lymphoma cells prompted the development of SYK inhibitors as a new class of anti-cancer drug candidates." (PMID 25506060, 2014). "SYK is capable of associating with and phosphorylating STAT3 in human B-lineage leukemia/lymphoma cells challenged with oxidative stress." (PMID 23021489, 2012). "SYK is of particular interest as a therapeutic target in leukemia and lymphoma as it plays a central role in activation of downstream kinases both via the BTK pathway and through its ability to directly phosphorylate and activate PI3K resulting in formation of second messenger PIP3 from PIP2." (PMID 36888611, 2023). "Moreover, SYK itself is known to be a master regulator of anti-apoptotic signaling in B-lineage leukemias and lymphomas with cell-cycle regulatory function by G2 checkpoint regulation." (PMID 33435587, 2021). "Since SYK activation is directly caused by mutated MYD88 and mediates its downstream STAT3 and AKT signaling, we next sought to clarify the importance of SYK in supporting cell growth and survival in MYD88-mutated lymphoma cells." (PMID 32005797, 2020). "The novel SYK and FLT3 inhibitor TAK-659 prevents the enlargement of spleen and tumor development in a mouse model of EBV-associated lymphoma by counteracting the activation of cellular kinase SYK through the viral LMP2A gene by inducing cell death in tumor cells but not in nontumor cells." (PMID 30135222, 2018). "The activation of SYK by LMP2A made premalignant cells and tumor cells very sensitive to the effects of TAK-659, as 60 nM TAK-659 completely inhibited SYK phosphorylation in the LMP2A-positive cells while inducing SYK phosphorylation in the LMP2A-negative MYC lymphoma cells." (PMID 30135222, 2018). "Therefore, SYK has emerged as a potential molecular target for treatment of B-lineage leukemias and lymphomas." (PMID 24851191, 2014). "A meta-analysis using the Oncomine database revealed a marked enrichment of the most discriminating SYK-dependent anti-apoptotic genes and confirmed STAT3 targets in 18 diagnostic classes of human leukemias and lymphomas, of which 5 were represented in multiple studies." (PMID 24851191, 2014). "Taken together, this meta-analysis strongly suggested that SYK activation could lead to the upregulation of anti-apoptotic genes and inhibitors of cellular differentiation in a variety of leukemias and lymphomas." (PMID 24851191, 2014). "SYK inhibition causes disruption of important signaling pathways such as BCR signaling pathway and mTOR pathway leading to apoptotic death in leukemia and lymphoma cells." (PMID 24851191, 2014). "As such, the oral SYK inhibitors cerdulatinib (Portola Pharmaceutical) and entospletinib (Gilead Sciences) are under active clinical investigation for the treatment of certain lymphomas, chronic lymphocytic leukemia, and acute myeloid leukemia (NCT01994382 and NCT02457598)." (PMID 35650195, 2022).